HS3ST6 (heparan sulfate-glucosamine 3-sulfotransferase 6)
Description:
Sulfotransferase that utilizes 3'-phospho-5'-adenylyl sulfate (PAPS) to catalyze the transfer of a sulfo group to heparan sulfate. The substrate-specific O-sulfation generates an enzyme-modified heparan sulfate which Unlike 3-OST-1, does not convert non-anticoagulant heparan sulfate to anticoagulant heparan sulfate. (Microbial infection) Acts as a binding receptor to Herpes simplex virus-1 (HSV-1) and permits its entry.
Synonyms: 3-OST-6; HS3ST5; 3OST6; HAE8
Tractability: Antibody: UniProt predicts a signal peptide or a membrane-spanning region.
Gene: Protein-coding gene on chromosome 16 (1,911,475 to 1,918,415, reverse strand). Ensembl gene ENSG00000162040.
Subcellular location: Golgi apparatus membrane
Pathways (Reactome):
Metabolism: HS-GAG biosynthesis
Gene Ontology:
Molecular function: [heparan sulfate]-glucosamine 3-sulfotransferase activity; sulfotransferase activity
Biological process: heparan sulfate proteoglycan biosynthetic process
Cellular component: Golgi membrane
Genetic constraint (gnomAD): Loss-of-function variants: 13 observed, 9.63 expected, observed/expected ratio (o/e) 1.35, 90% interval 0.87 to 1.89. That is too few expected variants to judge how well the gene tolerates losing a copy. Missense variants: 501 observed, 388.17 expected, observed/expected ratio (o/e) 1.29, 90% interval 1.2 to 1.39. Synonymous variants: 209 observed, 169.41 expected, observed/expected ratio (o/e) 1.23, 90% interval 1.1 to 1.38.
Homologues: Orthologues: macaque HS3ST6 (93% identical), dog HS3ST6 (91% identical), mouse Hs3st6 (90% identical), rat Hs3st6 (89% identical), pig HS3ST6 (86% identical), guinea pig HS3ST6 (85% identical), tropical clawed frog hs3st6 (67% identical), zebrafish hs3st3b1b (59% identical), chimpanzee HS3ST6 (59% identical), rabbit HS3ST6 (59% identical), zebrafish si:ch211-216b21.2 (58% identical), zebrafish hs3st3l (55% identical), and 2 more. Paralogues in human: HS3ST3A1 (62% identical), HS3ST3B1 (61% identical), HS3ST4 (57% identical), HS3ST2 (57% identical), HS3ST5 (35% identical), HS3ST1 (35% identical), NDST1 (30% identical), NDST4 (29% identical), NDST2 (29% identical), NDST3 (28% identical).
Diseases named in the same sentence as HS3ST6 in open-access papers:
HS3ST6 is named in the same sentence as 9 diseases in open-access papers, as found by Europe PMC text mining. Sharing a sentence is not in itself a finding about the gene and the disease. The quoted sentences say what the papers report.
hereditary angioedema (5 papers, 2021 to 2025). Hereditary angioedema (HAE) is a genetic disease characterized by the occurrence of transitory and recurrent subcutaneous and/or submucosal edemas resulting in swelling and/or abdominal pain. "For instance, HS3ST6 is involved in hereditary angioedema, characterised by acute episodic cutaneous or submucosal angioedema, often accompanied by abdominal pain." (PMID 39863470, 2025). "The group will then develop pathogenicity classification rules to curate variants in genes responsible for Hereditary Angioedema with normal C1-INH (nl-C1-INH-HAE), such as F12, PLG, ANGPT1, KNG1, MYOF, and HS3ST6 (OMIM: 610618, 619360, 619361, 619363, 619366, 619367)." (PMID 38124188, 2023). "Hereditary angioedema due to C1 Inhibitor deficiency shares a common kinin dependency with other HAE situations: F12-HAE, PLG-HAE, KNG1-HAE, ANGPT1-HAE, and HS3ST6-HAE, but not with MYOF-HAE, U-HAE." (PMID 35958943, 2022).
angioedema (2 papers, 2025). Swelling involving the deep dermis, subcutaneous, or submucosal tissues, representing localized edema. "While it is possible that some patients with these additional mutations may have been misclassified, it is unlikely considering the low frequencies of mutations in MYOF and HS3ST6 genes among patients with nC1INH angioedema." (PMID 40469312, 2025).
breast carcinoma (1 paper, 2025). "Upregulated genes included FoxO6 in endothelial cells, a transcription factor with limited evidence linking it to breast cancer, and Hs3st6, encoding an enzyme involved in heparan sulfate biosynthesis, a pathway known to influence tumour cell proliferation." (PMID 40925719, 2025).
cancer (1 paper, 2025). A tumor composed of atypical neoplastic, often pleomorphic cells that invade other tissues. "For genes robustly downregulated post pregnancy or during involution we identified Hs3st6, a member of the Heparan Sulfate 3-O-Sulfotransferase family observed in cancer but which remains poorly understood and Peg12, a paternally expressed gene also known as Frat3, of unknown function." (PMID 40925719, 2025).
HS3ST6 also shares sentences with these, for which no sentence is quoted: tumor (3 papers); glioblastoma (1); hepatocellular carcinoma (1); invasive breast ductal carcinomas (1); pancreatic cancers (1).